HIF1A (hypoxia inducible factor 1 subunit alpha)
Diseases named in the same sentence as HIF1A in open-access papers (continued):
Sharing a sentence is not in itself a finding about the gene and the disease.
Arthritis (continued). "Moreover, AnCar‐ExoLaIMTS3 can efficiently deliver therapeutic cargo to pro‐inflammatory macrophages and inhibit the synovial inflammatory response via downregulation of HIF‐1α level, thus ameliorating the severity of arthritis in vivo." (PMID 38083984, 2024). "Therefore, hypoxia has traditionally been considered a factor that exacerbates arthritis by inducing HIF-1α expression in RA." (PMID 33918929, 2021). "Here, we investigated the inhibitory effect of hypoxia on arthritis by controlling HIF-1α." (PMID 33918929, 2021). "In M1-polarizing conditions, 65–79*SE was predicted to stimulate activation of pro-inflammatory, pro-RA upstream regulators, such as Stat3, Rel, Rela, Jun, Ctnnb1 and Hif1a, among others, and to inhibit anti-arthritis or anti-inflammatory regulators (e.g. Klf2, Xbp1, Foxp3)." (PMID 33510427, 2021). "In contrast, conditional knockout of HIF-1α in myeloid cells can relieve experimental arthritis by reducing myeloid cell activation independently of VEGF, indicating that HIF-1α can also modulate the alleviation of arthritis and inflammation independently of its anti-angiogenesis effect." (PMID 28455825, 2019). "Although hypoxia and HIF-1α induction are observed in the synovium of arthritis, the special role of HIF-1α with molecular signaling in fibrosis is still unknown." (PMID 28003810, 2016). "We hypothesize that the addition of HA will alleviate inflammatory nociception and impede the accumulation of arthritis-induced HIF-1α, iNOS, and MMP3 production in the early phase of the experimental arthritic inflammatory joint." (PMID 21679445, 2011). "Therefore, expression of HIF-1α was increased in arthritis and may promote arthritis development by downstream signals." (PMID 36761171, 2022). "Utilizing HIF-1α inhibitors, such as Roxadustat, prevents IEC death, maintains intestinal barrier function, and improves arthritis symptoms." (PMID 39575238, 2024). "Previous studies have shown increased HIF-1α expression in CIA rats during the first immunization, suggesting its potential involvement in early angiogenesis in arthritis." (PMID 37715217, 2023). "Our study suggests, for the first time, that sustained hypoxia suppresses HIF-1α and pro-inflammatory cytokine expression in MH7A cells, while inhibiting arthritis in a CIA rat model." (PMID 33918929, 2021). "In animal models of arthritis, succinate has been shown to induce synovial angiogenesis through VEGF-dependent HIF-1α pathways." (PMID 32362840, 2020). "In consequence, HIF-1α expression in B cells regulates autoimmune diseases such as EAE and arthritis." (PMID 29343683, 2018). "Their findings reveal that HIF-1α can induce a switch from physiological cell apoptosis to pathological necrotic apoptosis by transcriptional inhibition of RIPK3, thereby initiating intestinal mucosal inflammation and exacerbating arthritis." (PMID 39575238, 2024). "Overall, we suggest that sustained hypoxia also suppresses arthritis via the negative feedback of HIF-1α." (PMID 33918929, 2021). "Succinate remodeled the HIF-1α/VEGF axis to induce synovial angiogenesis and suppressed succinate dehydrogenase (SDH) to prevent succinate accumulation results in inhibition of the HIF-1α/VEGF axis, showing the potential to attenuate revascularization in arthritis." (PMID 34940570, 2021). "Low-impact sustained hypoxia effectively delayed the onset of joint swelling, suppressed arthritis, and ameliorated cartilage pathological changes via negative feedback of HIF-1α." (PMID 33918929, 2021). "The abolition of succinate dehydrogenase (SDH) activity with dimethyl malonate limited succinate accumulation and prevented angiogenesis via blocking the HIF-1α/VEGF axis, revealing a new potential therapeutic strategy to attenuate neo-angiogenesis in arthritis." (PMID 32362840, 2020).
Arthritis (continued). "This may indicate that pyroptosis was involved in KOA and can be induced by elevated HIF-1α because LPS stimuli can mimic inflammatory environments similar to KOA and are often used to induce arthritis models." (PMID 30755787, 2019). "Therapeutically, fostering of HIF-1α expression may provide a tool to increase IL-10-producing B cells and limit autoimmune diseases such as EAE and arthritis." (PMID 29343683, 2018). "We identified HIF-1α as a critical transcriptional factor involved in IL-10 production by B cells, thereby influencing the course of T cell-mediated autoimmune diseases such as EAE and arthritis." (PMID 29343683, 2018). "Increased HIF-1α protein levels were detected in macrophages of RA patients and myeloid-specific deletion of HIF-1α reduces joint swelling and inflammatory activity in a murine arthritis model." (PMID 27034586, 2016). "This study demonstrated that early intervention of HA is an effective protection against accumulation of inflammation-induced HIF-1α, iNOS, and MMP3 and might limit the erosive joint damage of arthritis." (PMID 21679445, 2011).
injury (38 papers, 2014 to 2026). Damage inflicted on the body as the direct or indirect result of an external force, with or without disruption of structural continuity. "The plasma levels of TN-T and HIF-1α/TN-T are cardiac biomarkers with higher diagnostic accuracy for postmortem diagnosis of cantharidin-induced myocardial injury, VEGF/HIF-1α promises to be a biomarker for PMI estimation." (PMID 32694590, 2020). "Liu and collaborators showed that 4-HPA was able to reduce the levels of the pro-inflammatory cytokines TNF-α, IL-1β, IL-6, and HIF-1α and prevent lung oedema in a rat model of acute lung injury." (PMID 39000542, 2024). "The levels of SBDP145, melatonin, sLOX-1, HMGB1 and HIF-1α were highly expressed in preterm newborns with brain injury, and the levels were higher when the condition of the newborns was more severe." (PMID 39256844, 2024). "For severe TBI, approximately 70% of TBI patients suffered from cerebral hypoxia, and serum HIF-1α concentration highly correlated with poor outcome after head trauma." (PMID 36815939, 2023). "Such a pathway is responsible for many biological responses, including HIF-1α stabilization but also Nrf2 activation and the subsequent dampening of hyperoxia-induced detrimental effects such as lung injuries." (PMID 37686717, 2023). "These evidences suggest that BRP activates PI3K/Akt/HIF-1α signaling pathway to protect AHH-induced brain injury." (PMID 39282147, 2022). "Inhibition of the NF-κB and HIF-1α signaling pathways inhibited the expression of pro-inflammatory cytokines in rats with acute hypoxia-induced brain injury." (PMID 36434600, 2022). "Studies have found that S-nitrosoglutathione (GSNO) treatment stabilizes HIF-1α and induces the downstream gene expression of HIF-1α targets to stimulate regenerative processes, resulting in functional recovery in animals with mild traumatic brain injury." (PMID 35684364, 2022). "The expression of HIF-1α is increased to exhibit a protective effect after a traumatic spinal cord injury and a traumatic brain injury." (PMID 34502537, 2021). "While DOXO-induced oxidative stress and NF-κB activation are well documented, our findings are the first to demonstrate that selective AURKA inhibition can simultaneously downregulate the IL-17A-driven STAT3/HIF-1α/TGF-β1/VEGF-A axis in DOXO-induced liver injury." (PMID 40872590, 2025). "Repurposing existing drugs or developing new therapeutics that activate or modulate the CD133, EGFR, and HIF1A may offer promising treatment strategies for hypoxia-induced kidney injury." (PMID 40141116, 2025). "Under conditions of traumatic brain injury, Hif1α expression in the group treated with argon decreased by an average of 30% (p = 0.100), which may also indicate a moderate anti-ischemic effect of argon." (PMID 39684384, 2024). "The serum concentrations of SBDP145, melatonin, sLOX-1, HMGB1 and HIF-1α in newborns with different severity of ventricular hemorrhage were observed, and the levels of SBDP145, melatonin, sLOX-1, HMGB1 and HIF-1α in those with different severity of white matter brain injury were compared." (PMID 39256844, 2024). "Thus, we may conclude that, in our non-invasive hypoxia model, the moderate brain injury could be confirmed by an acute, significant decrease of Cox 4-1, and an increase of Hif-1α as markers of impaired cell oxygenation." (PMID 35295859, 2022). "Thus, the heme degradation products, CO and bilirubin, synergistically enforce metabolic reprogramming in the process of recovery following ischemic brain injury by increasing glycolytic activity, mitochondrial biogenesis, and angiogenesis via the HIF-1α/ERRα axis." (PMID 30153269, 2018).
injury (continued). "We demonstrated that HIF-1α CTAD−/− aggravated kidney injury in two independent mouse models of hypoxia-induced kidney injury, including ischemia/reperfusion-induced kidney injury and unilateral ureteral obstruction-induced nephropathy." (PMID 37225700, 2023). "A recent study in China shows that GL reduces the expression level of HIF-1α, inhibits the release of inflammatory cytokines IL-6 and TNF-α, and plays protective roles in acute lung injury." (PMID 35967372, 2022). "The levels of SBDP145, melatonin, sLOX-1, HMGB1, and HIF-1α in newborns with preterm brain injury were not dynamically analyzed, and further investigation into the dynamic changes of these markers is warranted." (PMID 39256844, 2024). "By systematic determination of the triterpenoids contained in ACT, we verified the protective properties of ACT against alcohol-induced liver injury in mice, which may be related to the ACT-induced modulation of the HIF-1α expression." (PMID 32719658, 2020). "Because HIF-1α, functioning as a transcription factor, is localized in the intracellular compartment, hypothetically, in response to acute brain injury, HIF-1α in the extracellular compartment may not be secreted from neurons but be released from destroyed neurons." (PMID 36570456, 2022).
kidney cancer (38 papers, 2012 to 2026). Primary or metastatic malignant neoplasm involving the kidney. "MiR-210, due to its regulation by HIF-1α a, is of particular importance in kidney cancer for the disruption the HIF-1α/VHL complex formation impaired by frequent VHL mutations in RCC." (PMID 35625614, 2022). "The paper further stated that loss of HIF1A (which is located at 14q23.2, and encodes HIF1α) was a target of 14q loss in kidney cancer (14q deletion is seen in up to 40% of ccRCC)." (PMID 33077781, 2020). "Loss of chromosome 3p, loss of chromosome 14q (harbors HIF1α) and gain of chromosome 5q (harbors p62) are the three most common genomic abnormalities in kidney cancer." (PMID 26743088, 2016). "In addition, downregulation of HIF1α in kidney cancer cells promotes tumor growth, while supplementing HIF1α deficient cell lines with HIF1α leads to tumor regression." (PMID 36040300, 2022). "HIF1A is a pathway targeted by kidney cancer susceptibility genes." (PMID 34289891, 2021). "To determine whether NleB could GlcNAcylate endogenous HIF-1α, we took advantage of the RCC4 cell line, an VHL-deficient kidney cancer cell line in which HIF-α (HIF-1α and HIF-2α) is highly expressed under normoxia." (PMID 30125331, 2018). "A predominant role in kidney cancer is played by inactivation of Von Hippen Lindau (VHL) tumor suppressor gene with consequent increased cellular amount of Hypoxia-Inducible Factor-1 alpha (HIF-1a) that cause abnormal cellular growth and angiogenesis." (PMID 27409344, 2016). "Likewise, HIF-1α has been implicated as a tumor suppressor especially in kidney cancer, even though substantial evidence in the literature support a critical role of HIF-1α in progression and metastasis." (PMID 25893706, 2015). "As previously reported, elevated Ndufa4l2 and Carbonic Anhydrase 9 (Car9) transcript levels are recapitulated in our TRACK (HIF1α) kidney cancer mouse model relative to normal kidney (WT)." (PMID 34970493, 2021). "To assay the contribution of HIF-1α to the opposing expression of MISTR1 (NDUFA4) and MISTRH, we leveraged that HIF-signaling is constitutively active in many kidney cancers due to loss of the Von Hippel–Lindau (VHL) tumor suppressor." (PMID 33370271, 2020). "It has been confirmed that fructose-1,6-bisphosphatase (FBP1) can bind to the inhibitory domain of HIF-1α and restrict the growth of kidney cancer by inhibiting glycolysis." (PMID 32928258, 2020). "Inhibition of HDAC4 in kidney cancer cells by specific short hairpin RNA resulted in increased acetylation and degradation, as well as reduced transcriptional activity of HIF-1α, as a result of HDAC4 reduction and subsequent acetylation of N-terminal lysines." (PMID 25608569, 2015). "Another example includes two antisense lncRNAs at the 5′ (5′aHIF-1α) and 3′ (3′aHIF-1α) ends of the human HIF-1α gene that are expressed in human kidney cancer tissues." (PMID 24238219, 2013). "HIF-1α is upregulated in many human cancers including colon, breast, gastric, lung, skin, ovarian, pancreatic, prostate, and kidney cancers; thus, inhibiting HIF-1α may result in anticancer effects by regulating cell growth, invasion, and migration." (PMID 40100307, 2025). "Preclinical animal experiments and cellular models have demonstrated that ET-1 could induce VEGF expression by increasing levels of hypoxia-inducible factor 1α (HIF-1α), which plays an important role in the development of kidney cancer." (PMID 40535814, 2025). "Together with HIF1α, it promotes glycolysis of kidney cancer cells, and the researchers also observed that PBRM1 deficiency can promote the proliferation, migration and invasion of 786-O and SN12C cells, and high levels of PB1 can prolong the life expectancy of kidney cancer patients." (PMID 39609317, 2024). "Likewise, HDAC4 can prevent the acetylation of HIF1A, thereby stabilizing the protein in human pVHL-null kidney cancer cell lines." (PMID 37998757, 2023).
kidney cancer (continued). "Furthermore, prior studies demonstrate that HIF-1α expression is often lost in ccRCC and that it actually has tumor-suppressive effects in the context of kidney cancer." (PMID 34609963, 2021). "In kidney cancer cells, the ability of mTOR to promote Hif1α translation has also been studied." (PMID 27148974, 2016). "Collectively, these data have significant implications for targeting the HIF pathway directly as it still remains unclear whether inhibition of HIF-1α or HIF-2α alone or in combination would be beneficial for kidney cancer." (PMID 24136229, 2013). "Given DoRothEA is not tissue specific, we sought to confirm that the HIF TFs bind to the target genes in ccRCC by using ChIP-seq data from HIF1A and EPAS1 (also known as HIF2A) in kidney cancer cell lines (see “Methods”)." (PMID 39633487, 2024). "For instance, HIF1A binds to MAX and disrupts MYC/MAX complexes, leading to reduced cyclin D2 expression, induction of p21 (CDKN1A), and G1 phase cell cycle arrest in human pVHL-null kidney cancer cell lines." (PMID 37998757, 2023). "A study analysing the role of HIF1α and -2α in inducing PD-L1 expression suggested that in kidney cancer, HIF2α is the main regulator of PD-L1 expression and not HIF1α." (PMID 37240301, 2023). "Analyses of the interplay of HIF and mTOR reveal that specific classes of HIF1A and HIF2A transcriptional target gene manifest different sensitivity to mTOR, in a manner that supports combined use of HIF2A and mTOR inhibitors in treatment of kidney cancer." (PMID 36097292, 2022). "Through in silico analyses of ChIP-seq dataset Cistrome we identified 7 candidate TFs among which HIF1A was reported to transcribe PFKFB4 in other cancers but was not validated in kidney cancer." (PMID 34593007, 2021). "As topoisomerase I inhibitors are potent inhibitors of HIF-1α, we were interested in whether CPT also inhibited HIF-2α, which is considered to be the more important subunit for kidney cancer progression." (PMID 24136229, 2013). "However, it does question the characterization and labeling of HIF1α as a ‘tumor-suppressor’ in kidney cancer based on experimental observations in models with no angiogenesis (in-vitro cell lines) or with deficient immune system (nude mice xenograft)." (PMID 33077781, 2020). "According to reports, in kidney cancer cells lacking VHL, HIF-1α can negatively regulate mitochondrial mass and O2 consumption." (PMID 32928258, 2020).